TNF (tumor necrosis factor)
Diseases named in the same sentence as TNF in open-access papers (continued):
Sharing a sentence is not in itself a finding about the gene and the disease.
Lewis lung carcinoma (27 papers, 1990 to 2025). "In Lewis lung carcinoma, TNF-α was found to induce SLPI expression, suggesting a feedback mechanism where SLPI modulates TNF-α’s inflammatory effects." (PMID 40284680, 2025). "TNFRSF9 is an important regulator of mast cell function in several pathologies, including Lewis lung carcinoma in mouse models, and TNF production and signaling in mast cells has been recognized as an important aspect of their function for decades." (PMID 37113661, 2023). "Knocking down TNFR2 in Lewis lung carcinoma cells combined with a low dose of recombinant mouse TNF significantly inhibited carcinoma growth in WT mice, suggesting that TNF/TNFR2 signaling in tumor cells is pro-tumorigenic in this transplantable tumor model." (PMID 33917839, 2021). "To extend our observations to another cancer model, we tested the effect of anti-PD-1 blocking antibodies in WT, TNF- and TNFR1-deficient mice injected with Lewis lung carcinoma (LLC) cells, which expressed MHC-I at low levels." (PMID 29273790, 2017). "Lewis lung carcinoma (LLC)-conditioned BMDMs also showed a significant increase in TNFα and CCL2 levels in response to LPS." (PMID 26177198, 2015). "In accordance with other studies using the Lewis lung carcinoma, we observed a systemic pro-inflammatory condition as characterized by elevated serum levels of Il-6 and TNF-α." (PMID 21637823, 2011). "By activating TLR2:TLR6 complexes and inducing TNF-α secretion in myeloid cells, versican strongly enhances Lewis lung carcinoma metastatic growth." (PMID 20145615, 2010). "Moreover, FLP also reduces serum TNF-α, IL-1β, and IL-6 level in a Lewis lung carcinoma xenograft mouse." (PMID 26597177, 2015). "For example, Lewis lung carcinoma (LLC) cells secrete factors which activate TLR2 in murine macrophages, mediating IL-6 and TNFα production and inducing lung inflammation." (PMID 33922955, 2021). "Extracellular matrix protein versican derived from Lewis lung carcinoma was found to activate bone marrow-derived macrophages by binding to TLR2, leading to secretion of inflammatory cytokines such as TNF-α to promote metastasis." (PMID 32382015, 2020). "Lewis lung carcinoma increased plasma concentrations of PAI-1 by 42% (p < 0.01) and TNF-α by 2.5 fold (p < 0.01) in wild-type mice compared to non-tumor-bearing controls fed the AIN93G diet." (PMID 27028862, 2016). "Remarkably, elevated levels of ZAG, as well as TNFα and IL-6, did not induce depletion of adipose tissue in Lewis lung carcinoma–bearing mice lacking adipose tissue triglyceride lipase (ATGL), pointing to a central role of ATGL in the pathogenesis of CAC." (PMID 24787299, 2014).
lipid metabolism disorders (27 papers, 2011 to 2025). "Elevated pro-inflammatory cytokines such as TNF-α and IL-6 have been linked to lipid metabolic disorders, while oxidative stress biomarkers including GSH, CAT, SOD, and MDA are widely recognized indicators of redox homeostasis." (PMID 41304686, 2025). "GSDF improves tissue inflammation in mice caused by lipid metabolism disorders by inhibiting the expression of IL-1β, TNF-α, and other cell proteins." (PMID 40428495, 2025). "GSDF increased the expression levels of PPAR-γ, AMPK, and P-AMPK proteins, and lowered the expression of IL-1β, TNF-α, and other proteins in the adipose tissues of the epididymis, in turn inhibiting adipogenesis and ameliorating lipid metabolism disorders." (PMID 40428495, 2025). "Research has identified similarities in decreased cell function, mitochondrial dysfunction, lipid metabolism disorders, chronic inflammation, and the role of pro-inflammatory cytokines like IL-1β and TNFα." (PMID 39176085, 2024). "At the same time, lipid metabolism disorder also promotes the production of a large number of cytokines, such as tumor necrosis factor (TNF-α), interleukin (IL-6) and adiponectin, which induces oxidative stress and inflammatory response." (PMID 37709801, 2023). "ALT, AST, IL-6, TNF-a, TC, TG, and FFAs levels significantly increased in the serum and liver tissues of cPtenf/fPck1f/f mice, suggesting more serious liver injury and lipid metabolism disorder in cPtenf/fPck1f/f mice." (PMID 36918564, 2023). "These targets play an important role in the PPI network and KEGG signaling pathway, and they have a significant impact on glucose, lipid metabolism disorders, and inflammation (such as TNF-α, AKT1, PPARG, and PTGS2)." (PMID 36199550, 2022). "These targets play an important role in the PPI network and KEGG signaling pathway, and they have a significant impact on glucose and lipid metabolism disorders and inflammation (such as TNF-α, AKT1, PPARG, and PTGS2)." (PMID 36199550, 2022). "TNF-α increases LDL levels and decreases HDL levels, thereby increasing the risk of lipid metabolism disorder." (PMID 36506546, 2022). "This study has demonstrated the increased inflammatory factors (IL-1β and TNF-α) and concluded that the inflammation may play a regulatory role in lipid metabolic disorders induced by DEHP." (PMID 31979393, 2020). "GM-CSF increases tumor necrosis factor-α and interleukin-1β gene expression, which could affect lipid metabolic disorders." (PMID 21486485, 2011). "Network pharmacology analysis identified TNF-α, IL-18, IL-1β and PPAR-γ as major targets of LPQ1 in lipid metabolism disorders." (PMID 40730505, 2025).
liver dysfunction (27 papers, 2010 to 2025). "The onset of liver dysfunction is mainly determined by cytokines released by the tumor, such as IL-6 and TNFα, and it generally provokes fever, weight loss and an unfavorable prognosis." (PMID 28915665, 2017). "Pretreatment liver injury was an independent poor prognostic factor in newly diagnosed DLBCL patients, correlating with increased serum levels of liver dysfunction-associated cytokines IL-2R, IL-6, IL-10, and TNF-α." (PMID 29109622, 2017). "The amount of proinflammatory cytokines including tumor necrosis factor (TNF)-α and interleukin (IL)-6 contribute to liver dysfunction." (PMID 30098593, 2018). "In the liver dysfunction group, patients had significantly higher level of IL-2R, IL-6, IL-10, and TNF-α, when compared with those in the normal liver function group." (PMID 29109622, 2017). "These two proteins (NF-κB and STAT3) are likely to play important roles in the liver inflammatory response and in the maintenance of homeostasis, induction of APP synthesis by stimulating cytokines such as IL-6 and TNF-α, and in inducing liver dysfunction." (PMID 23516407, 2013). "Interleukin‐1, IL‐6, IL‐18, interferon‐gamma, and TNF‐α play a key role in the pathogenesis of AOSD, and elevated IL‐1 and IL‐18 levels are closely associated with the systemic symptoms of AOSD, such as fever, rash, and liver dysfunction." (PMID 37397575, 2023). "One study showed that genipin improved liver dysfunction by inhibiting TNF-α production." (PMID 36768454, 2023). "But the second increase of TNF-α and IL-6 on day 10 in patients with severe liver dysfunction (group B) confirms this hypothesis." (PMID 28542386, 2017). "Of note, patients in the liver dysfunction group retained significantly higher levels of serum cytokines IL-2R, IL-6, IL-10, and TNF-α, compared with those in the matched control group (p = 0.003, p = 0.022, p = 0.045, and p < 0.001, resp.) and healthy volunteers (all p < 0.001)." (PMID 29109622, 2017). "In their cohort, the overall incidence of liver dysfunction attributed to HBV reactivation was 7.3%, with a median onset of 32.4 months following the initiation of anti-TNF-α treatment." (PMID 40566546, 2025). "The current finding of elevated TNFα in AUD + HCV is consistent with reports of hospitalized alcoholics showing correlations between high TNFα levels and liver dysfunction." (PMID 29408932, 2018). "Also, higher serum levels of liver dysfunction indexes (i.e. ALP, AST, ALT, and GGT), immunological index AMA-M2, and inflammatory factors IFN-γ and TNF-α were noticed in PBC patients relative to the healthy control group." (PMID 36396948, 2022). "Values of TNF-α revealed a statistically significant negative correlation with the liver dysfunction on days 2 and 10 as indicated by Spearman’s coefficient of -0.537 (d2; P = 0.003) and -0.460 (d10; P = 0.027)." (PMID 28542386, 2017). "Firstly, the consequence of I/R injury include transient liver dysfunction and the systemic inflammatory response to syndrome, the indicators that reflected the systemic cytokines such as IL-6 or TNF levels in the sera from the blood samples of mice were not given." (PMID 30279567, 2018). "The negative correlations between TNF-alpha and total bilirubin, ALT, and MVP might be indicative of liver dysfunction." (PMID 37629267, 2023). "Both D-gal and actinomycin D induced TNFα-dependent hepatotoxicity and SEB-induced shock models using these agents encountered much higher levels of TNFα not present when SEB was used alone and liver dysfunction was a prominent feature in these models." (PMID 22069668, 2010).
myeloid leukemia (27 papers, 2003 to 2026). A clonal proliferation of myeloid cells and their precursors in the bone marrow, peripheral blood, and spleen. "It was recently shown that in U937 human myeloid leukemia cells, increased exposure to TNFα caused a down regulation of SOD1." (PMID 21655261, 2011). "Further functional assays conducted in an immunocompetent setting, both ex vivo and in vivo, demonstrated that HDAC6 inhibition sensitized murine myeloid leukemia cells to broad CD8+ T cell activation as evidenced by increased TNFα and CD107a expression." (PMID 41794832, 2026). "As an inflammatory mediator, TNF-α has been shown to promote the conversion of myeloid leukemia cells to macrophages and has been used in combination with all-trans retinoic acid to treat myeloid leukemia." (PMID 37210530, 2023). "Since the nuclear translocation of p50 and p65 directly regulates NF-κB downstream target genes, we further assessed the nuclear translocation of p50 and p65 in PHF6 KD myeloid leukemia cells in response to TNFα treatment by immunofluorescence." (PMID 37393343, 2023). "We did not observe any difference in the nuclear translocation of p65 in PHF6 KD myeloid leukemia cells and control cells after TNFα treatment." (PMID 37393343, 2023). "It has been shown that TNF-α enhances the differentiation of myeloid leukemia cells along a monocyte/macrophage pathway." (PMID 34681898, 2021). "Consistent with this, in FANCC-deficient murine hematopoietic stem cells, TNF-αoverproduction results in bone marrow hypoplasia, and long-term exposure of these cells to TNF-α induces clonal evolution that leads to myelogenous leukemia." (PMID 21912593, 2011). "Kamijo reported that TNF(C-Phe), in which the C-terminal leucine of TNF molecule was replaced by phenylalanine, was 20-times as potent in induction of differentiation of human myelogenous leukemia cells (U-937 cells) as the parent TNF(N-Met)." (PMID 15485573, 2004). "Consistent with our results, previous studies have shown that probiotics such as L. reuteri 6475 can suppress the ERK1/2 pathway in tumor necrosis factor-treated human myeloid leukemia-derived cells, and that a multispecies probiotic product increased the bcl-2 levels in constipated mice." (PMID 33362802, 2020). "Moreover, in FANCC-deficient murine hematopoietic stem cells, overproduction of and hypersensitivity to TNF-α results in bone marrow hypoplasia and long-term exposure of these cells to TNF-α induced clonal evolution that led to myelogenous leukemia." (PMID 21912593, 2011). "Based on our previous studies demonstrating that stable expression of hGH in cell lines could mimic the effect of exogenous GH, we exposed our two hGH-producing human myeloid leukaemia U937 cell lines and the control one to TNF-α during 2-day cultures." (PMID 12966434, 2003). "Moreover, another study found that CPT could sensitize TNF-α-induced apoptosis through ROS-dependent activation of Caspase-8 and p38 in human myeloid leukemia KBM-5 cells." (PMID 28654902, 2017). "Further, rFIP-mco can significantly reduce the expression levels of TNF-α, IL-1β, and IL-6 in the THP1 cells (human myeloid leukemia mononuclear cells)." (PMID 33193329, 2020). "TNF-α suppressed the proliferation of AML cells and patient myeloid leukemia cells effectively, IFN-γ can act in in synergy with TNF-α." (PMID 31849658, 2019). "Conversely, we showed that inhibition of MMP-9 largely restored the levels of NKG2D-, NKp30- and Perforin-positive NK-92 cells, the secretion of TNF-α and IFN-γ and the cytotoxicity on NK cells against myelogenous leukemia K562 cells." (PMID 25274283, 2014). "Some scholars, such as Li, have suggested that cytokines such as tumor necrosis factor, interferon, and interleukins secreted by HIV-infected cells promote the malignant transformation of cells and may lead to myeloid leukemia." (PMID 40028267, 2025).
myeloid leukemia (continued). "Notably, the overall amount of p50 was similar in PHF6 KD myeloid leukemia cells and control cells in the presence or absence of TNFα, while the nuclear p50 and p65 significantly decreased after TNFα treatment in PHF6 KD Kasumi-1 and K562 cells when compared with the control cells respectively." (PMID 37393343, 2023). "One such phosphosite, MAVS Ser222, has been reported after stimulation of human myeloid leukemia cells with TNF, which was an unexpected finding since MAVS is not known to be a part of TNF signaling pathways." (PMID 37238738, 2023). "Our data further confirmed that the production of TNF-α and IFN-γ by NK cells in response to K562 myeloid leukemia cells was not affected by ECP treatment." (PMID 30949182, 2019).
Peptic ulcer (27 papers, 2011 to 2025). The term peptic ulcer refers to acid peptic injury of the digestive tract, resulting in mucosal break reaching the submucosa. "Considering the comorbidities are associated with older age, such as peptic ulcer and cardiovascular disease, physicians are often reluctant to prescribe effective drugs such as NSAIDs and TNF-α inhibitors to patients with LOAS." (PMID 34732807, 2021). "IL-1β is a key factor in triggering and amplifying inflammation, and a low IL-1β level coupled with a high TNF-α level may increase the risk of peptic ulcer disease in H. pylori infections." (PMID 39354365, 2024). "The association between a low IL-1β level and an increased TNF-α level might be considered a risk factor for peptic ulcer disease in the setting of H. pylori infection." (PMID 35884067, 2022). "Furthermore, individuals with blood group O was found to had higher risk to peptic ulceration due to an increasing density of colonization of epithelial cells and higher inflammatory responses (release of IL-6, IL-10 and TNF-α) to H. pylori.." (PMID 29088730, 2017). "Moreover, the authors concluded that the association between a decrease in the IL-1β level, along with an increase in TNF-α, might be considered a risk factor for peptic ulcer disease in the setting of H. pylori infection." (PMID 35884067, 2022). "Our study showed a significant elevation in the serum TNF-α levels in the peptic ulcer untreated group compared to the normal control group (356.3 ± 1.14 vs. 194.8 ± 0.86, respectively)." (PMID 36542210, 2022). "The involvement of TNF-α in the etiopathogenesis of peptic ulcers might be explained by its chemotactic effect on T and B cells and the consecutive progression to peptic ulcers." (PMID 35884067, 2022). "Additionally, there was a significant increase in the serum levels of TNF-α and IL-1β in untreated peptic ulcer rats." (PMID 36542210, 2022). "Inflammation is a pivotal pathological reaction of ethanol-related peptic ulcer, which is mainly characterized by increased secretion of diverse proinflammatory factors, such as TNF-α, IL-6, and IL-1β, and inhibition of the production of anti-inflammatory cytokines such as IL-10." (PMID 32325708, 2020). "Therefore, the serum levels of IL-6 and TNF-a are closely related to the changes of peptic ulcer." (PMID 33235586, 2020). "The PPI network was constructed for the peptic ulcer genes, the constructed network to show the interactions between peptic ulcer targets proved that the following genes have the higher node degrees; AKT1, TNF, SRC, EGFR, ESR1, PTGS2, MMP9." (PMID 38728332, 2024). "It has been long known that TNF-α is significantly higher in patients with H. pylori infection than in healthy controls, as well as in those with histologically demonstrated gastritis and peptic ulcers, suggesting that it might contribute to the gastric injuries caused by this infection." (PMID 35884067, 2022). "Infiltration of macrophages and neutrophils, and the release of pro-inflammatory cytokines (such as TNF-α, IL-1β and MCP-1) significantly affect the healing and recurrence of peptic ulcer." (PMID 29095895, 2017). "Thus, TNF is not required for protection against peptic ulceration induced by piroxicam." (PMID 21858200, 2011).